CRP (C-reactive protein)
Diseases named in the same sentence as CRP in open-access papers (continued):
Sharing a sentence is not in itself a finding about the gene and the disease.
leukocytosis (continued). "At admission, his C-reactive protein (CRP) concentration was 7.17 mg/dl (normal value <0.5 mg/dl) and he had leukocytosis (white blood cells (WBC) 19.36 × 103/μl) and neutrophilia (15.77 × 103/μl; 81.4%)." (PMID 28003031, 2016). "The most frequent features include leukocytosis, elevated ESR and CRP levels, and polyclonal gammopathy." (PMID 27142277, 2016). "In a recent study, leukocytosis has been reported only in 36% of children, increased ESR (cutoff value 20 mm/h) in 91%, and elevated CRP value (cutoff value 20 mg/dL) in 81% of them." (PMID 27240392, 2016). "The patient showed a severe hypoxemia (pH 7.36, PaO2 5.6 kPa, PaCO2 6.4 kPa), leukocytosis and mild increase of LDH, CRP, and procalcitonin serum levels." (PMID 26861356, 2016). "Characteristic laboratory features include anemia (usually hypochromic and microcytic), leukocytosis, thrombocytosis, elevated immunoglobulins, increased erythrocyte sedimentation rate (ESR) and C-reactive protein (CRP), and hypoalbuminemia." (PMID 27999545, 2016). "Laboratory examination revealed leukocytosis (WBC: 28300/uL), segmented predominance (segment: 67 %) and an elevated CRP level (CRP: 69.4 mg/L)." (PMID 27234442, 2016). "Laboratory examinations revealed leukocytosis (WBC 24 × 103/μL, neutrophils 84.9%), increase of inflammatory indexes (CRP 14.68 mg/dL, ESR 64 mm/h), ferritin (3147 ng/mL), and transaminases (AST/ALT 83/99 U/L); CK was normal." (PMID 25767733, 2015). "Leukocytosis was found in patients with a median WBC count of 11.9 × 109/L (7.0-28.1 × 109/L), and CRP in patients had a median count of 106.9 mg/L (28.8-311.0 mg/L)." (PMID 25886859, 2015). "Specifically, inflammatory markers, such as CRP, ESR, and leukocytosis, as well as rheumatological markers such as ANA were analyzed for patients with a positive abnormal finding on VCE and those without any abnormal findings on VCE." (PMID 25893440, 2015). "Laboratory parameters in KD patients include leukocytosis with thrombocytosis, elevated erythrocyte sedimentation rate (ESR), C-reactive protein (CRP) level, transaminase level, and hypoalbuminemia." (PMID 23893035, 2014). "Laboratory examinations revealed leukocytosis (white blood cell (WBC) counts: 20,410/μL), high absolute neutrophil counts (ANCs: 10,880/μL), and high levels of C-reactive protein (CRP: 6.39mg/dL)." (PMID 25488491, 2014). "We found leukocytosis (71.42%), polynucleosis (90%), elevated ESR (84.61%), elevated CRP (92.30%) during the early episode of fever in patients who were tested." (PMID 25793068, 2014). "The only abnormal laboratory findings were leukocytosis (WBC counts: 14,460/μL) and high ANCs (10,450/μL), but CRP levels were only slightly elevated (1.81mg/dL)." (PMID 25488491, 2014). "Diagnosis of the systemic inflammatory response to infection is based mainly on clinical status and biochemical markers including leukocytosis and increases in plasma levels of procalcitonin (PCT), C-reactive protein (CRP) and lactate." (PMID 24043287, 2014). "Laboratory findings: Laboratory findings are mild leukocytosis, elevated ESR and CRP, and high level of serum IgD in 66% of patients and elevated IgE level in 50% of patients." (PMID 25793039, 2014). "The presentation of pustular skin lesions, splenic abscesses, leukocytosis, elevated ESR, and CRP suggested an infectious etiology in our patient." (PMID 25276144, 2014). "Laboratory tests revealed leukocytosis (11,880/μL, neutrophils 75.6%), increase of erythrocyte sedimentation rate ([ESR] 36 mm/h), α2-globulins (1.08 g/dL), C-reactive protein ([CRP] 2.4 mg/dL), and ACPAs positivity (>250 U/mL)." (PMID 25501069, 2014). "A laboratory examination revealed leukocytosis (white blood cell count [WBC]: 11,900/mm), normocytic normochromic anemia (Hb: 6.1 g/dL), elevation of C-reactive protein (CRP) level (6.1 mg/dL), and renal dysfunction (BUN: 42.6 mg/dL, Cr: 4.04 mg/dL)." (PMID 24558622, 2013).
leukocytosis (continued). "Other indicators are positive blood culture (only found in 35.6%), leukocytosis, elevated erythrocyte sedimentation rate (ESR), and elevated C-reactive protein (CRP)." (PMID 24383049, 2013). "Leukocytosis (WCC), an elevated C-reactive protein (CRP) and erythrocyte sedimentation rate (ESR), and recent unexplained hyperglycemia are all systemic responses to infection." (PMID 23898912, 2013). "Laboratory tests showed leukocytosis (WBC: 16.000/ mm3) and elevation of the C-reactive protein (CRP: 22 mg/dl)." (PMID 24171067, 2013). "Few classic and rare laboratory findings include neutropenia or leukocytosis, mild thrombocytopenia, eosinophilia, elevated acute phase reactants such as ESR and CRP, low complement levels C3 and C4, and elevated circulating immune complexes such as C1q." (PMID 23056053, 2012). "The patients can have leukocytosis, anemia, raised erythrocyte sedimentation rate (ESR) and elevated C-reactive protein (CRP)." (PMID 21489283, 2011). "Laboratory evaluation revealed leukocytosis (26,500/μl) with 47% neutrophils and an elevated erythrocyte sedimentation rate (ESR) (57 mm/1st hour) and C-reactive protein (CRP) (100 mg/l)." (PMID 20727148, 2010). "Laboratory investigations often indicate an ongoing inflammatory process with a leukocytosis and a raised ESR and CRP, as was evident in our case." (PMID 20718986, 2010). "Blood leukocytosis (25,050/μl) with neutrophilia (71%) and elevated ESR (100 mm/1st hour) and CRP (30 mg/l) were the main laboratory findings." (PMID 20727148, 2010). "The laboratory tests revealed anemia, leukocytosis, thrombocytosis, erythrocyte sedimentation rate (ESR) of 120 mm in the first hour, C-reactive protein (CRP) of 47 mg/dl (normal £ 0.5) and ferritin level of 230 ng/ml (normal £ 140)." (PMID 20169282, 2009). "Labs showed leukocytosis (WBC: 12.22 × 109/L, neutrophils: 8.91 × 109/L) and CRP of 289 mg/L." (PMID 42292015, 2026). "Laboratory tests revealed leukocytosis, elevated ESR and CRP, and hyperuricemia." (PMID 42317512, 2026). "Laboratory findings typically reveal systemic inflammation with elevated levels of C-reactive protein (CRP) and a higher erythrocyte sedimentation rate (ESR), significantly increased ferritin levels (3–5 times above normal), and leukocytosis, primarily with neutrophilia." (PMID 39941651, 2025). "Laboratory tests revealed leukocytosis at 14,580/mm3, C-reactive protein (CRP) at 122.7 mg/L, no electrolyte disturbances, and liver and kidney function tests showed no abnormalities." (PMID 41466919, 2025). "Blood test results showed leukocytosis (WBC 13.04 × 109/L) and elevated CRP (144.44 mg/L)." (PMID 40672036, 2025). "Laboratory findings were generally nonspecific, although anemia, leukocytosis, elevated C-reactive protein (CRP), and liver enzyme abnormalities were occasionally reported." (PMID 40765583, 2025). "Leukocytosis of 24,160 cells/μL with a left shift and c-reactive protein (CRP) level of 215 mg/L were noted, with no other significant laboratory alterations." (PMID 40699062, 2025). "Regarding nonspecific immunological responses, leukocytosis, CRP, or serum levels of IL-6 or procalcitonin at admission were not a differentiating factor." (PMID 40076968, 2025). "Complete blood count showed leukocytosis (white blood cell count 28.14 × 109/L) and neutrophilia (absolute neutrophil count 26.9 × 109/L, 95.6 %), with a C-reactive protein level of 385 mg/L, but no bacteria were detected in blood cultures." (PMID 39866529, 2025). "During acute exacerbations, patients may exhibit an elevated erythrocyte sedimentation rate (ESR), C-reactive protein (CRP) level, and leukocytosis." (PMID 41181478, 2025). "All reactions were associated with a slight to moderate elevation in C-reactive protein (CRP) levels (up to 27 mg/L), without accompanying leukocytosis." (PMID 41001152, 2025).
leukocytosis (continued). "Initial laboratory examination revealed leukocytosis, elevated C-reactive protein (CRP), elevated D-dimer, and anemia, without thrombocytopenia or renal failure." (PMID 41458710, 2025). "Leukocytosis was significantly associated with HAP but had low specificity, while CRP showed a non-significant trend." (PMID 40257674, 2025). "Laboratory results indicated leukocytosis and elevated ESR and CRP, suggestive of infection." (PMID 41210013, 2025). "Laboratory investigations revealed no leukocytosis and neutrophilia, with a C-reactive protein (CRP) <1 mg/L." (PMID 40443641, 2025). "Traditional markers such as leukocytosis and CRP are helpful but nonspecific for complicated appendicitis." (PMID 41230472, 2025). "Laboratory tests at the time of hospitalization showed marked leukocytosis with a left shift, elevated C-reactive protein (CRP), and worsening renal function, but no abnormalities in the coagulation profile." (PMID 41303165, 2025). "Laboratory findings at the time of admission demonstrated leukocytosis without concomitant elevation of inflammatory markers, such as C-reactive protein." (PMID 39925586, 2025). "Inflammatory burden further influenced prognosis, with leukocytosis (WBC >18,000/mm3) and elevated CRP emerging as significant predictors of amputation, consistent with earlier studies linking heightened systemic inflammation to extensive tissue necrosis, deep infection, and poor limb salvage." (PMID 41367432, 2025). "Laboratory testing for Case-1 revealed leukocytosis (WBC 18,600/μL) and elevated CRP (58.3 mg/L)." (PMID 41011403, 2025). "Initial labs revealed leukocytosis with a WBC count of 23.5 ×109/L, neutrophil predominance (84.2%), thrombocytosis (platelets 458 ×109/L), hypo-osmolarity (260.5 mOsm/kg), and elevated inflammatory markers including CRP >15 mg/L and ESR 71 mm/hr." (PMID 40901212, 2025). "Initial labs revealed elevated inflammatory markers [erythrocyte sedimentation rate (ESR) 52 mm/hour, C-reactive protein (CRP) 5.25 mg/L], mild anemia, hypoalbuminemia (1.6 g/dL), normal complement levels, and no leukocytosis." (PMID 40253385, 2025). "C-reactive protein levels remained stable, peaking at admission (5.74 mg/dL), without leukocytosis, and the patient remained afebrile throughout hospitalization." (PMID 40034639, 2025). "A triad of fever, nausea and vomiting, and flank pain are the most common symptoms, in addition to nonspecific laboratory results such as elevated CRP, abnormal urine analysis, and leukocytosis." (PMID 41377458, 2025). "Inflammatory markers (CRP and ESR) were elevated, accompanied by leukocytosis and lymphocytosis." (PMID 41283383, 2025). "Laboratory analysis revealed relative lymphopenia, without leukocytosis or eosinophilia, and a C-reactive protein (CRP) level of 16.64 mg/dL (reference range: 0-0.5 mg/dL)." (PMID 41409912, 2025). "Inflammatory markers like leukocytosis and elevated C-reactive protein (CRP) levels are commonly observed, but they are non-specific and should prompt clinicians to consider imaging as the next step in diagnosis." (PMID 40589634, 2025). "Initial laboratory evaluation revealed leukocytosis (WBC 18.5 × 109/L; reference range: 4.0-11.0 × 109/L), elevated C-reactive protein (CRP 23.9 mg/L; reference range: <5.0 mg/L), and thrombocytosis (platelet count 671 × 109/L; reference range: 150-400 × 109/L)." (PMID 40062024, 2025). "Other acute phase proteins such as C-reactive protein were not measured in this study, but most dogs enrolled had a leukocytosis, primarily due to neutrophilia with left shift." (PMID 40538729, 2025). "These include elevated C-reactive protein (CRP), anemia, elevated transaminases, hypoalbuminemia (≤3.0 g/dL), hyponatremia, thrombocytosis (platelet count > 450,000/μL), leukocytosis (white blood cell count ≥ 15,000/μL), cerebrospinal fluid pleocytosis, and sterile pyuria." (PMID 40868207, 2025).
leukocytosis (continued). "During this admission, she was noted to have leukocytosis (WBC 14.5x109 cells/L, normal 4-11x109 cells/L) and elevated CRP (251 mg/L, normal <8.1 mg/L), but was afebrile and had negative blood and urine cultures and sexually transmitted blood-borne infections panel." (PMID 38957514, 2024). "The present case was preceded by leukocytosis and increase over time in NLR and CRP levels." (PMID 39158760, 2024). "Laboratory examinations typically show leukocytosis with neutrophilia, thrombocytosis, anemia, and an elevation in inflammatory markers such as erythrocyte sedimentation rate (ESR), C-reactive protein (CRP), and serum ferritin." (PMID 39463675, 2024). "As leukocytosis may be a normal finding in pregnant women, Laboratory tests such as white blood cell count (WBC) and C-reactive protein (CRP) may also be of limited value, as mild leukocytosis including a slight left shift is frequently found during pregnancy." (PMID 39466332, 2024). "The duration of a postoperative leukocytosis or CRP increase was not significantly related to bacterial detection." (PMID 39064142, 2024). "Laboratory tests revealed leukocytosis (12,000 mm3) with a left shift (73% neutrophils), hemoglobin level of 11 g/dL, platelet count of 404,000 mm3, and an elevated inflammatory marker (CRP—C-reactive protein—84.720)." (PMID 39195006, 2024). "The most common laboratory abnormalities were elevated inflammatory markers (ESR 91%, CRP 80.5%), with or without leukocytosis (35.9%)." (PMID 39158233, 2024). "Among the inflammatory markers, there was no leukocytosis or elevated c reactive protein in both groups." (PMID 38528535, 2024). "Inflammatory markers such as leukocytosis and CRP were similarly elevated after decannulation, regardless of the infectious condition." (PMID 39797141, 2024). "Gastrointestinal basidiobolomycosis should also be part of differential diagnosis in patients with abdominal mass, weight loss, and other features of chronic infection or cancer, such as anemia thrombocytosis, leukocytosis, and high inflammatory markers (ESR and CRP)." (PMID 39867099, 2024). "The complete blood count was normal without leukocytosis (WBC: 9600 K/μλ) while the C-reactive protein (CRP) was elevated (CRP: 21.59 mg/L with a cut-off limit for pregnancy at 15 mg/L)." (PMID 38673673, 2024). "Given the absence of leukocytosis, a negative procalcitonin, and a favorable response to symptomatic therapy, and despite markedly elevated C-reactive protein levels, antibiotics were not administered." (PMID 39065145, 2024). "In the absence of leukocytosis and significant procalcitonin elevation, antibiotic therapy was avoided despite high CRP levels." (PMID 39065145, 2024). "His labs showed elevated erythrocyte sedimentation rate (ESR) at 48 mm/hr and a C-reactive protein (CRP) at 15.3 mg/L, in the absence of leukocytosis (WBC at 7.61x10e3/mcL)." (PMID 39221398, 2024). "Further tests revealed no leukocytosis, a CRP level of 52 mg/dL, a negative urine culture, and a positive blood culture for L. monocytogenes." (PMID 39597695, 2024). "Laboratory investigations showed an elevated C-reactive protein (CRP 186.2 mg/L) without leukocytosis." (PMID 39328789, 2024). "Contrary to our expectations, the severity of leukocytosis, C-reactive protein levels, and highest body temperature did not indicate the risk of acute encephalitis." (PMID 38528535, 2024). "POC CRP evaluates inflammatory reactions, and POC CBC assesses leukocytosis." (PMID 38434607, 2024). "Clinically, the patient remained afebrile with no leukocytosis and resolution of the elevated CRP during this time." (PMID 39483118, 2024). "Laboratory findings showed non-specific leukocytosis with an elevated C-reactive protein (CRP) level of 8.09 mg/dl and an electrolyte sedimentation rate of 120 mm/h." (PMID 39233764, 2024). "Initial blood tests revealed mild leukocytosis, slightly elevated C-reactive protein (CRP), and a negative D-dimer." (PMID 39845240, 2024).
leukocytosis (continued). "Blood tests were notable for elevated C-reactive protein (CRP) and leukocytosis." (PMID 39584846, 2024). "Several hours previously at the initial visit to the regional hospital, she had no fever, even though she showed leukocytosis and a marked increase of CRP as severe inflammatory signs." (PMID 39741600, 2024). "A portion of them had anemia and thrombocytosis, while leukocytosis or elevated hs-CRP was not common." (PMID 38783946, 2024). "Laboratory results showed leukocytosis and elevated C-reactive protein, but blood cultures were negative." (PMID 39410513, 2024). "Laboratory studies revealed mild leukocytosis (11,570/μL) and neutrophilia (6870/μL), with a negative C-reactive protein (CRP), normal renal function, normal lactate dehydrogenase (LDH), and unremarkable urinalysis." (PMID 39651033, 2024). "Of the 105 patients with probable acute bacterial colitis, 93 (88.6%) of them presented with elevated CRP levels (normal range: <8 mg/L), and 38 (36.9%) of 103 children who obtained a complete blood count (CBC) presented with leukocytosis (WBC count: >10,000/μL)." (PMID 38397283, 2024). "Laboratory findings of altered coagulation profiles, elevated levels of C-reactive protein (CRP), leukocytosis, and hyperglycemia are common; however, they do not sufficiently distinguish it from other SSIs." (PMID 39845828, 2024). "Leukocytosis, platelet count, and serum C-reactive protein (CRP) were used to measure non-specific inflammation." (PMID 38275389, 2023). "C-reactive protein levels were mildly elevated at 2.35 mg/dL (normal range, 0–0.9 mg/dL) without leukocytosis, and she showed no fever." (PMID 37808331, 2023). "Patients with EP, MIVOD, or IMHMV often present with leukocytosis and elevated CRP levels, but there are no specific laboratory markers." (PMID 36741906, 2023). "In our study, 17.4% of the patients had leukocytosis, and 80% had elevated CRP, but these differences were not statistically significant." (PMID 38052876, 2023). "Laboratory findings include leukocytosis, elevated LDH, elevated CRP, and microscopic hematuria." (PMID 37038580, 2023). "Compared to survivors, a significantly higher number of non-survivors had leukocytosis (60% vs 21.9%, p = 0.016), elevated CRP (100% vs 61%, p = 0.010), and acute kidney injury (40% vs 7.6%, p = 0.010) at the time of admission." (PMID 37056528, 2023). "In this study, males and females were compared, and fever was the most common prehospital symptom in males; laboratory findings showed leukocytosis and hyperbilirubinemia, higher ALT, creatinine, and CRP levels, and lower D-dimer levels in males than in females." (PMID 36769766, 2023). "The features of leukocytosis, left shift in neutrophil count, CRP concentration, and negative urine analysis are determined by the laboratory." (PMID 37951984, 2023). "Leukocytosis (>11 × 109/L), the value of C-reactive proteins (CRP) (>8 mg/L) and neutrophilia are non-specific findings and have little diagnostic value, but combined, these parameters have a very high sensitivity for the diagnosis of acute appendicitis." (PMID 37238435, 2023). "Besides leukocytosis with neutrophilia, common laboratory findings include increased ESR, elevated levels of CRP, elevated ferritin (indicating macrophage activation), elevated transaminases, as well as decreased serum albumin." (PMID 36876221, 2023). "Laboratory findings include an increase in CRP and ESR, leukocytosis with neutrophilia, and anemia." (PMID 36876221, 2023). "Her C-reactive protein levels were mildly elevated at 2.35 mg/dL (normal range, 0–0.9 mg/dL) and no leukocytosis was shown (6.78 × 109/L)." (PMID 37808331, 2023). "Initial blood tests revealed moderate leukocytosis with neutrophilia and eosinophilia, thrombocytosis, and normal CRP levels; an HIV test was negative." (PMID 36821021, 2023). "Among the published cases, four of nine patients displayed autoimmunity with chronically elevated CRP and leukocytosis without any evidence of infection." (PMID 37833669, 2023).